CCR2 (C-C motif chemokine receptor 2)
Diseases named in the same sentence as CCR2 in open-access papers (continued):
Sharing a sentence is not in itself a finding about the gene and the disease.
tumor (continued). "However, our data suggest that the recruitment of reprogrammed, trained CCR2+ monocytes/macrophages exert robust anti-tumor effects." (PMID 35140221, 2022). "However, the GVAX + αPD-1 and CCR2/5i + αPD-1 treatment groups significantly enhanced IFN-γ production from CD8+ T cells isolated from the tumor and spleen compared with CCR2/5i alone." (PMID 35404390, 2022). "While initial correlative studies had shown a reduction in TAMs and influx of tumor-infiltrating lymphocytes, subsequent analyses demonstrated that CCR2 inhibition resulted in compensatory increases in CXCR2+ TANs, putting into question the rationale of targeting a single myeloid subset." (PMID 36077755, 2022). "In mice, subcutaneous injection of a CCR2 inhibitor (PF-04136309) ablated inflammatory monocytes and macrophages not only in the primary tumor but also in the pre-metastatic niche, leading to decreased tumor growth and metastases, as well as improved anti-tumor immunity." (PMID 35740692, 2022). "Chronic inflammation during senescence might enhance tumor growth by recruiting myeloid-derived suppressor cells using the CCR2 cytokine receptor." (PMID 35325182, 2022). "CCR2 is involved in promotion of tumor-supportive immune microenvironment." (PMID 36033829, 2022). "Furthermore, SBRT followed by αPD-1 + CCR2/5i also maintained tumor growth control in most of the mice during the later course of ultrasound observation, perhaps to a greater degree than SBRT followed by αPD-1 alone." (PMID 35404390, 2022). "However, UPS tumors in the CCR2 KO group demonstrated quicker tumor volume and BLI response to treatment." (PMID 36700206, 2022). "In addition, CCL2 and CCL7 are expressed on GBM and enable CCR2+ cells to play a tumor-recruiting role." (PMID 36466873, 2022). "The results showed a decrease in miR-125b relative expression as the number of mast cells infiltrated in the tumor increased, which we hypothesized could be mediated by increased Ccr2 expression levels." (PMID 35565345, 2022). "In Kaposi sarcoma, it has been shown that activation of the K-Ras-B-Raf-ERK pathway results in downregulation of ACKR2 expression, unleashing CCR2-mediated recruitment and activation of M2-like phenotype of macrophages, which support angiogenesis and tumor growth via producing VEGFA." (PMID 35677043, 2022). "Moreover, the blockage of CCR2 inhibited macrophage liver infiltration, which, in turn, resulted in a reduction of tumor growth due to an increase of cytotoxic CD8+ present at the tumor site." (PMID 35409139, 2022). "CCL2/CCR2 blockade has little effect on established TAMs and still promotes tumor progression." (PMID 35585567, 2022). "However, when HCC was established, tumor cells inhibited the differentiation of infiltrating CCR2+ immature myeloid cells, which in turn promoted tumor growth, via the inhibition of NK cells." (PMID 35008390, 2022). "TAMs recruited in CCR2-dependent manner contribute to the tumor development." (PMID 36733385, 2022). "This could be at least partially reversed by combined targeting of CXCR2 and CCR2, demonstrating a critical role for collagen and CAFs in the orchestration of the tumour microenvironment (TME)." (PMID 35533046, 2022). "We analyzed the expression of CCR2, a key chemotactic receptor on monocytes responsible for their recruitment into tumor mass, and CD163, a clearance receptor for hemoglobin-haptoglobin complex, which expression on TAMs correlates with tumor growth and metastasis in various cancers including CRC." (PMID 36733385, 2022). "Regardless of whether clodronate liposomes were administered, we found a large population that consisted of 20–70% CX3CR1+F4/80+ cells, which may indicate some inference by TRMs, and a 5–15% CCR2+F4/80+ population was found in the tumor." (PMID 35326625, 2022). "It has been suggested that CCL2 might act as an autocrine or paracrine chemokine to promote the growth of tumor cells, which can be partially abolished by CCR2 antagonists or PI3K inhibitors." (PMID 35702353, 2022).
tumor (continued). "It has been reported that CCL2 mediates tumor angiogenesis in two main ways: CCL2 can bind to CCR2 directly, leading to angiogenesis, and CCL2 may indirectly promote angiogenesis through the recruitment of macrophages." (PMID 36077785, 2022). "CCL2 is a chemokine that attracts a number of CCR2-high-expressing monocytes to the tumor site." (PMID 35592338, 2022). "Bartneck’s study demonstrated that immunosuppressive TAMs are abundant in the center of HCC and that CCR2+ TAMs accumulate at the highly vascularized border of tumor; In vivo experiments showed that inflammatory and angiogenic pathways are activated in CCR2+ TAMs." (PMID 36093115, 2022). "Moreover, a CCR2 antagonist has been shown to inhibit tumor growth, reduce tumor size and prevent recurrence after resection in a liver cancer experimental model." (PMID 36712976, 2022). "When the CCL2/CCR2 interaction was blocked, the metastatic dissemination of tumors in the mouse was significantly inhibited, the survival of the mouse was prolonged and the expression levels of tumor-promoting cytokines were reduced." (PMID 36131942, 2022). "Tumor-educated MSCs release large amounts of chemokines, including C-C chemokine ligand-2, C-C chemokine ligand-7, and C-C chemokine ligand-12, thereby accelerating the recruitment of CCR-2 dependent monocytes and macrophages to the tumor, which finally promotes tumor growth." (PMID 36439438, 2022). "CCR2 inhibition was previously shown to counteract metastasis and tumor growth in a murine model." (PMID 35740692, 2022). "Generally, tumor cells and tumor-associated stroma are rich sources of CCL2, the ligand for CCR2." (PMID 33603130, 2022). "In addition, we selected three pairs of tumor tissues and adjacent tissues to examine, and the results of Western blotting indicated that CCR2 expression was increased in tumor tissues compared with adjacent tissues." (PMID 36497150, 2022). "The CCL2/CCR2 axis is involved in the recruitment of monocytes and macrophages to tumor sites." (PMID 36403057, 2022). "We further employed several transgenic mouse strains and adoptive bone marrow transfer experiments to show that effective pharmacologic KRAS blockade in vivo is dependent on the presence of CCR2+ (C-C motif chemokine receptor 2) IL-1β-secreting myeloid cells in the tumor microenvironment." (PMID 35327394, 2022). "Next, tumor tissues from both groups of mice were collected and subjected to immunohistochemical histostaining, and we observed a significant decrease in the number of cells positive for GOT1, CCR2, Nrf2 and HO-1 proteins in tumor tissue sections from mice with knockdown of GOT1 expression." (PMID 36497150, 2022). "Furthermore, we obtained four genes (GIMAP6, CD80, IL16, and CCR2) that had predictive advantages for tumor purity using random forest classification and random forest regression." (PMID 35280857, 2022). "There has been increasing evidence that monocytes are essential premetastatic promoters and are rapidly recruited from the bone marrow, mainly via the CCL2/CCR2 axis, to premetastatic niches, where they promote tumor colonization by secreting angiogenic factors such as VEGFA." (PMID 36460981, 2022). "However, later in the course of ultrasound observation, most mice in the groups treated with SBRT followed by CCR2/5i alone or αPD-1 + CCR2/5i + GVAX had uncontrolled tumor growth." (PMID 35404390, 2022). "The CCR2/CCL2 is a known recruitment axis for tumor associated macrophages and highly expressed by TAO1 cells in culture we utilized a CCR2 KO model, which leads to deficiencies in monocyte recruitment into tumors and has been shown reduced tumor macrophages in previous work." (PMID 36700206, 2022). "Furthermore, both the tumor weight–normalized cell number and the percentage of TAMs among myeloid cells in the RT + αPD-1 + CCR2/5i group were reduced significantly compared with the RT + αPD-1 group." (PMID 35404390, 2022).
tumor (continued). "Moreover, combining the CCR2 antagonist (RS504393) with anti-PD-1 resulted in an enhanced tumor response compared to anti-PD-1 monotherapy in multiple murine tumor models." (PMID 36679900, 2022). "Tumor-specific subtypes as revealed by single-cell technology include early immigrant macrophages (HLA-DR+CD192+), monocyte resembling immature macrophages (CCR2+), tissue-resident macrophages (CD206+HLA-DR+), TAMs (CD64+HLA-DR+), and myeloid-derived suppressor cells (MDSC; HLA-DR−/low)." (PMID 33763348, 2021). "The role of CCR2 seems to outreach the influence on TAM recruitment at the tumor site." (PMID 33919517, 2021). "Thus, although Tregs are not the sole type of T cells expressing CCR2, the net outcome of CCR2 antagonism in T cells favors the anti-tumor arm of immune responses." (PMID 34804061, 2021). "Together, the data supports that CCR2 represents a major Treg homing receptor in tumor contexts." (PMID 34804061, 2021). "Additionally, VCAM-1 binding peptide tagged liposomes carrying the CCR2 antagonist can reduce pre-metastatic lung vascular permeability by directly targeting cancer cell-activated endothelium, and thereby prevent tumour cell extravasation." (PMID 35006432, 2021). "Accordingly, in murine breast cancers, monocyte/macrophages are major MMP-9 producers and have a strong impact on cancer cell extravasation since MMP-9 expression and cancer extravasation are strongly reduced in tumor mice ablated of CCR2+ inflammatory monocytes." (PMID 33783686, 2021). "Likewise, in an orthotopic model of PDAC, immunosuppressive CCR2+ macrophages were recruited to the liver during tumor progression where they established a metastatic niche." (PMID 34201127, 2021). "Altogether, these results revealed that KLRG1, BTK and CCR2 may interact through cell surface receptor signaling pathway to influence the proliferation of tumor cells or affect the immune response indirectly." (PMID 34187403, 2021). "According to our results, CCR2 seemed to be an anti-tumor factor for EC." (PMID 34251980, 2021). "Similar to chemotherapy, Radiotherapy could induce the CCR2-dependent recruitment of monocytes and CCR2+ Tregs into the tumor." (PMID 34804061, 2021). "Since CCL2 secreted by tumors could not become a chemoattractant towards CCR2low CD8+ T cells, generation of the functional CCR2-expressed CAR-T cells were reported to better localize in the tumor microenvironment." (PMID 34386431, 2021). "Murine MDSCs might also express disparate combinations of chemokine receptors, notably CX3CR1, CXCR2, CXCR4, and/or CCR2, which are critical for migration of MDSCs from the bone marrow and/or recruitment to tumor niche or sites of infectious disease." (PMID 34525267, 2021). "Further study found that blocking CCR2 inhibits tumor development." (PMID 34527668, 2021). "Multiple inhibitors or antibodies against CCR2 are being tested clinically as tumor treatment." (PMID 33919979, 2021). "On the other hand, CCL2/CCR2 has been shown to exert both pro- and anti-tumor effects." (PMID 34187403, 2021). "Either blockade of CCL2/CCR2 or β-AR signaling in EE mice lose the tumor protection capability." (PMID 34593796, 2021). "Indeed, in the mammary PyMT model, newly tumor-infiltrated blood CCR2+ monocytes are recruited by cancer cell– and stromal cell–derived CCL2." (PMID 33783686, 2021). "For example, in a study of pancreatic malignancy, it was shown that the CCR2 inhibitor PF-04136309 combined with FOLFIRINOX chemotherapy could achieve an objective tumor response and was safe and well tolerated." (PMID 34178692, 2021). "We then examined expression of CCL2/CCR2 signaling proteins in hDCIS.01 breast lesions." (PMID 33888841, 2021). "Further, the same contrast of deletion vs inhibition could also apply to CCR2 expressing Tregs and tumor cells." (PMID 34804061, 2021). "In addition, CCL16 ectopic expression significantly stimulated tumor growth and tumor volume, which was prevented by CCR2 knockdown." (PMID 33500726, 2021).
tumor (continued). "We surmise that two main types of suppressive immune cells (e.g. monocytic myeloid suppressors and Treg cells) in suppressive tumor microenvironments, are more dependent on CCR2 signaling and thus the net outcome of CCR2 signaling favors tumor progression and metastasis." (PMID 34804061, 2021). "The CCR2-CCL-2 axis is another pathway important in tumor-mediated myeloid recruitment." (PMID 33917501, 2021). "The CCL2/CCR2 pathway contributes significantly to the migration of M-MDSCs to tumor sites." (PMID 34620838, 2021). "In addition, CCR2-deficient MDSCs and the deletion of CCL2 reduced the recruitment of MDSCs into tumor sites of murine tumor models." (PMID 34441758, 2021). "Enhanced tumor trafficking effect of CAR-T by expressing CCR2 could be a potential strategy in combination with other CAR-T modification approaches to improve CAR-T therapy." (PMID 34386431, 2021). "Tumor samples were divided into high and low groups by median of CCR2 expression." (PMID 33949150, 2021). "Blockade of the CCL2/CCR2 pathway could effectively suppress the accumulation of TAMs in experimental tumor sites, and improve efficacy in combination with chemotherapy." (PMID 34248142, 2021). "CCL2 is a chemokine that attracts high CCR2-expressing monocytes to the tumor site." (PMID 33919517, 2021). "Additionally, in a clinical trial on PDAC, an objective tumor response was observed in 16 of the 33 patients (49%) receiving a CCR2 inhibitor (PF-04136309) plus FOLFIRINOX, compared to FOLFIRINOX alone." (PMID 34094963, 2021). "Furthermore, upon combination treatment with CCR2 antagonist and the immune checkpoint inhibitor PD-1 antibody, suppression of tumor growth was found to be more effective compared with the PD-1 antibody alone." (PMID 34394072, 2021). "However, in established HCC, peritumoral CCR2+ MoMFs enhance tumor growth through the inhibition of NK cells." (PMID 34831182, 2021). "Moreover, recent research has revealed that CCR2 expression on tumor cells orchestrates suppression of the immune response through impeding the infiltration and activation of cytotoxic T lymphocytes and CD103+ cross-presenting DCs." (PMID 33919979, 2021). "In our study, the expression of CCR2 was positively correlated with patients’ survival which indicated that CCL2/CCR2 axis may play anti-tumor effects in LUAD." (PMID 34187403, 2021). "The CCR2/CCL2 axis also plays a particularly important role in attracting monocytes, which, after interactions with tumor- and stromal-derived factors, differentiate into suppressive tumor-associated macrophages at the site." (PMID 34646829, 2021). "Following RS 504393 treatment, the number of TAMs and the tumour volume were significantly reduced in tumour‐bearing mice, suggesting that targeting CCR2 with RS504393 might be a potential therapeutic option for cancer." (PMID 34464477, 2021). "However, the CCL2/CCR2 axis seems to play a dual role in early tumor immunosurveillance and progression." (PMID 33540898, 2021). "Notably, the expression levels of KLRG1, BTK, CCR2, SCML4 were all associated with neoplasm disease stage (American Joint Committee on Cancer Code) (P = 0.001; P = 0.022; P = 0.004; P = 0.014, respectively)." (PMID 34187403, 2021). "However, conventional T cells accepting tumor antigens show low CCR2 expression compared with Tregs, which indicates a specific function of tumor antigens on Tregs." (PMID 34386431, 2021). "Thus, targeting the recruitment of immunosuppressive monocytes/macrophages to tumors by CCR2 antagonism has recently been investigated as a strategy to modify the tumor microenvironment and enhance anti-tumor immunity." (PMID 34804061, 2021). "Two families of chemokines—CC (CCL-2, 3, 5) and CXC (CXCL-1, 2, 5, 6, 8)—employ CCR-2 with monocytes and CXCR-2+ with neutrophils, at the tumour spot which distinguishes between TAMs and tumour-associated neutrophils (TANs), wielding either pro- or antitumour response." (PMID 34336101, 2021).
tumor (continued). "CCR2 antagonists or knockout of CCL2 in tumor cells significantly reduced metastatic tumor burden." (PMID 34067719, 2021). "Furthermore, ablative radiotherapy increased the production of tumour‐derived CCL2 in a pancreatic ductal adenocarcinoma model, and the increased CCL2 promoted the recruitment of Ly6C+CCR2+ monocytes in tumour sites, thereby accelerating tumour development." (PMID 34464477, 2021). "In breast cancer, CCR2+ MDMs also facilitate tumor metastasis." (PMID 33919979, 2021). "Numerous studies also revealed that CCR2 might play reverse roles in different kinds of tumors, either promoting tumor immune evasion or enhancing the anti‐tumor immune response." (PMID 33949150, 2021). "Of note, G-MDSCs were still decreased in the tumor tissue from CCR2−/− mice housing in EE." (PMID 34593796, 2021). "In fact, inhibition of CXCR2 and CCR2 could reverse tumor progression promoted by type I collagen deletion in myCAFs as was evident in a PDAC mouse model potentially by cytotoxic T cell trafficking." (PMID 34646829, 2021). "In addition, there was a decrease of circulatory CCR2+ monocytes, an increase of bone marrow CCR2+ monocytes, a reduction of TAMs in tumor tissues and modulation of the TME (increase in IL-12 and TGF-α, and a decrease in IL-10, TGF-b, IL-13)." (PMID 34988021, 2021). "The CCL2/CCR2 axis is employed to mediate the splenic recruitment of HSPCs in tumor-bearing mice." (PMID 32582203, 2020). "The CCL2/CCR2 axis plays a vital role in the recruitment of TAMs to tumor tissues." (PMID 33224886, 2020). "In addition, tumor-bearing wild-type mice treated with a CCR2 inhibitor demonstrated a significant decrease in liver metastasis compared with vehicle or gemcitabine-only treated mice." (PMID 31297636, 2020). "Indeed, it was found that although targeting CCR2+ TAMs or CXCR2+ TANs alone can enhance anti-tumor immunity, unfortunately, this leads to a compensatory influx of alternative myeloid subset, which result persistent immunosuppressive TME." (PMID 33224886, 2020). "Additionally, bone marrow-derived hematopoietic stem cells expressing type 2 C-C chemokine receptor (CCR2+ HSCs) preferentially migrate to tumor tissues and differentiate into APCs in the tumor microenvironment." (PMID 32000802, 2020). "Targeting MCP-1/CCR2 signaling may alter the tumor microenvironment and enhance angiogenesis in cancer." (PMID 33330077, 2020). "We inoculated ID8 tumor cells into the peritoneal cavity of Ccr2+/+ and Ccr2–/– mice." (PMID 32780724, 2020). "Surprisingly, the frequency of tumor-associated MDSCs was not decreased in CCR2 antagonist-treated mice, but the MDSCs now displayed significantly lower levels of CCR2 expression and had an M1 phenotype." (PMID 33322474, 2020). "In addition to a change to an M1 phenotype of the CCR2+ MDSCs in mice treated with the CCR2 antagonist, we were surprised to find considerable CCR2 expression by the tumor cells themselves." (PMID 33322474, 2020). "Hence, the CCR2/CCL2 axis has been identified as an interesting target for tumor therapy, and collected data indicate that CCR2/CCL2 signaling plays a relevant role in the tumor-myeloid cell-interaction." (PMID 32668709, 2020). "Thus, expression patterns of Ccl2 and Ccr2 indicated that inflammatory signals were inhibited in the TRAMP-C1-derived tumor microenvironment." (PMID 32244522, 2020). "In addition, tumor-derived CCL2 can directly act on CCR2 positive endothelial cells to increase their permeability or indirectly via increasing CXCL12 expression, which helps CXCR4 positive cancer cells to extravasate into the PMNs." (PMID 33414786, 2020). "Chemokines and their receptors play an important role in directing cognate T-APC interactions in lymph nodes and spleen (e.g., CCR7 and CCL21/19), or in bone marrow (e.g., CXCR4 and CXCL12 (SDF-1α/β), or attracting Treg cells towards tumor tissue (e.g., CCR2 and CCL2 (MCP-1))." (PMID 32155856, 2020).